IL6 (interleukin 6)
Diseases named in the same sentence as IL6 in open-access papers (continued):
Sharing a sentence is not in itself a finding about the gene and the disease.
tumor (continued). "These antitumour effects were closely correlated with IFN-γ responses of OVA-Ip (tumour)-specific CD8+ T cells, which was not affected by anti-IL-6 Ab administration, although aged CD8+ T-cell responses were decreased as compared with young ones because of their quantitative decline in CD8+ T cells." (PMID 25850032, 2015). "Our recent studies found that high expression of SOCS3 could reduce tumor metastasis, EMT markers and STAT3 activation in the absence of IL-6 stimulation in CCA cell lines." (PMID 26485275, 2015). "Analysis of the profiles of cytokines in the culture supernatants showed that the tumor-activated γδ T cells secreted substantially more Th1-prone cytokines such as IFN-γ, IL-1, IL-6, and IL-12, but not IL-4 and IL-10, than peripheral-derived γδ T cells did (n = 5)." (PMID 24741609, 2014). "Interestingly, q-PCR revealed that the expression levels of IL-1β, IL-6 and MIP-2 as well as IFN-γ and TNF (data not shown) in the colonic tissue, especially in the tumor area, were suppressed by the treatment with ML-7 as well as with MP6-XT22." (PMID 24520376, 2014). "The results showed that G-CSF/IL-6 could not antagonize the priming effect of IFN-γ/TNF-α, evaluated by the activation of signaling pathways, MPO release, and tumor-suppressing effect of neutrophils." (PMID 25587026, 2014). "Interestingly, we also found that NC+IL6 macrophages expressed high levels of CD86 and exhibited no obvious tumor-promoting M2 phenotype function." (PMID 25313135, 2014). "ELISA analysis showed that DRibbles stimulation, similar to LPS, could significantly increase the levels of IL-6, IL-10 and TNF-α, whereas whole tumor cell lysate stimulation could not." (PMID 23326458, 2013). "In contrast, deletion of IKKβ gene in myeloid cells attenuated inflammatory responses and diminished expression of proinflammatory cytokines including TNF, IL-1, IL-6, and CXC chemokines, without affecting apoptosis while it resulted in a significant decrease in tumor size." (PMID 24212934, 2011). "Although a number of other TDF have been linked to diverse elements of MDSC biology, namely VEGF, GM-CSF, IL-1β, IL-6, PGE2, IFN-γ, SCF or IL-17, none have been rigorously tested to explain the connection between granulocytic MDSC response and tumor growth." (PMID 22110722, 2011). "However, in multivariate analysis used to age, gender TNM stage, tumor size and peritoneal metastasis, TTP and OS showed that IL-6 was not related to TTP and OS." (PMID 19457231, 2009). "Surprisingly, even in a model of noninflammatory tumor formation(DEN-induced hepatocarcinogenesis), NF-κB activation in macrophages (Kupffer cells) appears to stimulate tumorigenesis through the secretion of hepatomitogens such as TNFα and IL-6." (PMID 18615187, 2008). "In UVB-induced skin carcinogenesis, such redox modulation may reduce oxidative stress and attenuate downstream pro-inflammatory and pro-proliferative pathways, including IL-6/STAT3 and ERK/JNK, thereby preferentially affecting tumor promotion rather than UV photoproduct-driven initiation." (PMID 41596287, 2026). "Synthesizing these findings, the increase in IL-6, IL-8, and CSF1 levels in the TME upon CAF clearance in the huB12-MMAE context primarily drives the formation of a pro-inflammatory microenvironment rather than directly promoting angiogenesis or tumor proliferation." (PMID 41154598, 2025). "In addition, ADRr tumor cells showed more formation of p-STAT3/MSN complex that translocated to the nucleus compared to the TNBC cell lines without ADR resistance and the complex was enhanced by IL-6 stimulation." (PMID 40696387, 2025). "Whereas INFG and other cytokines, such as IL-6 and IL-10, did not exhibit any significant increase, this implies that the elevated levels of CXCL10 triggered by light may contribute to tumor regression." (PMID 39080467, 2024).
tumor (continued). "Moreover, we found that FXR upregulates IL-6 and IL-6ST expression but not IL6Rɑ, thus suggesting that IL-6/IL-6ST may mediate FXR-modulated Jak2/STAT3 activation and tumor metastasis in NSCLC." (PMID 38360812, 2024). "Modules 1–5 were rich in cytokines (e.g., IL6, IL10), cytokine receptors (e.g., CCR2, CCR4), and immune cell markers (e.g., CD3D, CD3E), indicating that the DEGs primarily regulate the immune microenvironment rather than tumor malignancy traits like proliferation and invasion." (PMID 38594692, 2024). "SC144 did significantly reverse M-BMDM-promoted tumor growth with no observed inhibitory effects for LLC alone group, indicating that early SC144 treatment suppresses tumor growth mainly by interfering with IL-6/gp130/STAT3 cascade in M2 macrophages, but not in tumor cells." (PMID 38274367, 2024). "However, we observed a significant induction of S100a14 suggesting that although IL-6 and LIF may contribute to tumor features, they do not directly contribute to EMT." (PMID 36828915, 2023). "Thus, a localized IR can elicit a systemic response that is mediated by cytokines and chemokines (TNF a, IL-1, IL-6, MCP-1, IL-8) and activate T cells directed against tumor-specific antigens, infiltrating both irradiated and non-irradiated tumor localizations." (PMID 37345088, 2023). "The authors are of the opinion that despite GBP therapy not affecting tumor development, the effects of GBP at the molecular level, such as increased SOD activity, IL-6 and MCP-1 levels and reduced arginase activity, may have a positive effect on the patients’ general condition." (PMID 36835284, 2023). "Indeed, the IL-10 production by the tumor is able to counteract the tumoricidal effect of the pro-inflammatory cytokine IL-6 secreted by macrophages by inducing, via SOCS3, negative feedback on the IL-6 signaling." (PMID 37835437, 2023). "Notably, the transfer of CART19-28z SNX9 KO was accompanied with increased serum levels of anti-tumor effector molecules IFNγ, Perforin, and Granulysin, while we detected a decrease in IL10 and IL6 (human CCL5 could not be detected in the serum)." (PMID 36732507, 2023). "NF-kB-induced IL-6 stimulates STAT3 activation in intestinal epithelial cells and promotes tumorigenesis in CAC through the inhibition of apoptosis and induction of cell proliferation, although IL-6 does not have significant effect on early tumor promotion in the CAC." (PMID 38273841, 2023). "Indeed, pituitary IL-6 may provoke contrary effects (inhibitory or stimulatory) in different tumours such as ACTH-, PRL-, GH-secreting and non-functioning tumours." (PMID 35837315, 2022). "Herein, we determined that IL-6 was significantly upregulated in CRC tissues relative to normal controls, and we determined that such IL-6 expression was negatively correlated with miR-370 levels and positively correlated with circRNA_101277 levels within these tumor tissues." (PMID 35356749, 2022). "While immunological tumor cell death with NCX4040 is not known at this time, our recent results using microarray analysis with low doses of NCX4040 indicate that NCX4040 significantly induces IL-6 gene and other immune responses genes (NFkB, TNF, etc.)in OVCAR-8 and NCI/ADR-RES cells." (PMID 35955744, 2022). "Moreover, IL-6 knockdown by siRNA technology in HEp-2-CSCs decreased not only IL-6 expression levels, but STAT3 and HIF1 as well, leading to the suppression of LSCC proliferation, colony formation, invasion, and tumor growth, and inducing apoptotic cell death." (PMID 35406495, 2022). "Interestingly, investigators found the therapeutic benefit of anti-IL-6 antibody to be dependent on CD8+ T cells, as CD8-depleted mice did not demonstrate the reduction in tumour size or increase in survival that were observed in control mice and CD4-depleted mice following anti-IL-6 treatment." (PMID 33803414, 2021).
tumor (continued). "In a study using prostate-specific phosphatase and tensin homolog (Pten)−/− mice, we found that an HFD doubled the tumor weight in the model mice but did not increase tumor weight in mice administrated celecoxib, a cyclooxygenase-2 (COX-2) inhibitor, or an anti-interleukin (IL)-6 antibody." (PMID 32093338, 2020). "We noted that IL-6- and HIL6-stimulated mammosphere cultures showed an increase in the relative abundance of CD44high/CD24low cells, a phenotype that has been ascribed to neoplastic and nontumorigenic mammary cells enriched in tumor-initiating and sphere-forming cells, respectively." (PMID 33020483, 2020). "Furthermore, this CSC population secretes IL-6 to a much greater extent than non-SCs, which leads to a feedback loop that can be interrupted by an IL-6 receptor antibody, reducing the CSC population, tumor growth and metastasis." (PMID 33059744, 2020). "In the present study, we found that the expression of IL-4, IL-6, TNF-α, and IFN-γ but not IL-10 dramatically increased after T cell interaction with peptides+HB100-108/pulsed DCs, indicating that this vaccine design has the ability to activate allogeneic T cells against tumor antigen." (PMID 32322595, 2020). "Properties of quercetin, and other identified compounds, that reduce IL-6 and IL-10 show promise as a potential anti-cancer therapeutic, though reductions in TNF and IL-12 may not be favourable for anti-tumour activity as these cytokines can promote the anti-tumour response." (PMID 32183059, 2020). "In this study, No significant increase in IL-6 was observed in IRE–NK group, indicating that NK cell immunotherapy could regulate and improve the cellular immune response, positively regulate the immune system function and improve the anti-tumor effect." (PMID 30151798, 2019). "The phenomenon that PGE2 potentiates the production of CCL2 and simultaneously reduces CXCL8 production by GM-CSF/IL-6 M-MDSC, could explain the observation that M-MDSC accumulate preferentially in PGE2-rich tumor site, rather than PMN-MDSC, although this hypothesis needs to be tested independently." (PMID 30936876, 2019). "This IL-6-dependent metabolic shift is absent in DU145 cells, where the Warburg effect is probably maintained through the HIF-1α/PKM2/STAT3 axis, further confirming the distinctive response to the inflammatory cytokine of these two differently staged tumor cell lines." (PMID 31500219, 2019). "In line with the expectation that cell types of the microenvironment such as macrophages rather than hepatocytes or tumor cells mainly produce IL-6, we could not find a significant effect of SMAD7 overexpression on the production of Il-6 mRNA or secretion of IL-6 in HuH-7 cells." (PMID 28134936, 2017). "Further investigation showed that BsAb could strongly inhibit inflammatory factor production in vivo compared with control mice, including IL-6, although TNF-α was not reduced by BsAb, which may alleviate chronic inflammation during the progress of tumor treatment." (PMID 28404966, 2017). "Thus, an IL-6-driven inflammatory feedback loop is a core epigenetic regulator of the dynamic equilibrium that converts non-stem cancer cells into CSC-like cells, and generates tumor heterogeneity in genetically distinct cancer cells." (PMID 28529938, 2017). "Particularly, a significant reduction in tumor sizes was shown in STC1/IL-8-High tumor (31% reduction versus STC1/IL-8-Normal, p = 0.025), but not in STC1/IL-6-High cases (22% reduction versus STC1/IL-6-Normal, p = 0.245), which may due to the small sample size of the STC1/IL-6-High cohort." (PMID 26469082, 2015). "Moreover, the expressions of VEGF, MIP-2, TGF-β1, IL-6, and IL-8 were all up-regulated in GCN-MSCs and BM-MSCs by 10 % BGC-823-CM or MKN-28-CM stimulation, suggesting a converted progression suffered by MSCs from non-malignant tissues by tumor cells." (PMID 25986392, 2015).
tumor (continued). "Our results show that the serum levels of IL-6 were only slightly affected by tumor at day 28, while the serum levels of IFN-γ were not increased, and serum TNF-α was undetectable (data not shown) in 4T1 tumor-bearing mice up to day 28 after tumor cells implantation." (PMID 25822717, 2015). "The results showed that TNF-α and IL-6 productions by monocytes incubated with NVD at different concentration levels (5000 and 2500 μg/mL) increased in vitro, but the proliferation activity of monocytes and tumor cell toxicity did not seem to be affected by NVD." (PMID 26339270, 2015). "Moreover, the expression levels were unaffected by PDT or RelA knockdown, altogether indicating that IL-10 and IL-12 did not modulate IL-6 and TNF-α signaling and did not play a role in the PDT response by tumor cells or the immunogenicity of PDT-afflicted EMT-6 cells in macrophages." (PMID 26307977, 2015). "Therefore, reduced levels of IL-6 in response to neutrophil depletion, CXCR2 inhibition, or lack of NE could be considered as another mechanism of tumor regression." (PMID 24321240, 2013). "Co-culturing of tumour cells and fibroblasts in 3D conditions did not result in the appearance of new cytokines; rather, the amounts of certain cytokines already upregulated in 3D mono-cultures, such as GCP-2, IL-6, amphiregulin, GRO/GRO-α, IL8, and MSP-α, were further increased." (PMID 20723242, 2010). "However, the authors pointed to a previous study suggesting that IL-6 promotes the induction of Th17 cells and therefore, the blockade of IL-6 may restore the balance of the Th17-Treg axis without affecting Th1-CD8+ T cells, that are required for effective tumor anti-tumor immunity." (PMID 39247203, 2024). "In addition, evidences suggest that IL-6 trans-signaling, but not IL-6 classic signaling, is essential to promote HCC carcinogenesis and progression, and only the activation of membrane-bound IL-6R and gp130 in hepatocytes seems not sufficient for tumor formation." (PMID 38890694, 2024). "Furthermore, the classification between the non-tumor and the tumor groups could be more correctly predicted by including information of Vpr and anti-Vpr IgG into age, CD4, CD8, HIV viremia, HBV, viremia, HCV viremia, IL-6, and TNFα." (PMID 38166062, 2024). "Furthermore, tumour cells and non-malignant stromal cells secrete different growth factors such as TGF-β1, EGF, vascular endothelial growth factor (VEGF), FGF, TNF-α, IL-1β, and IL-6 that promote CAF trans-differentiation and activation, contributing to a pro-inflammatory profile and carcinogenesis." (PMID 34830058, 2021). "Furthermore, the expression of cytokines IL-1β and IL-6 in the GC + PTT group was both 1.7-fold higher than that in the PBS + PTT group, whereas, the expression of the cytokine IL-4 with a pro-tumor function was not significantly different between all the groups." (PMID 32042338, 2020). "Moreover, our results also indicate a significantly positive correlation among leptin, IL-6, TNF-α and HGF and TNM stage, and a significantly negative correlation between adiponectin and TNM stage; suggesting that it should be considered as an important factor in tumor growth." (PMID 29088874, 2017).
infection (7,495 papers, 1993 to 2026). The state of being infected such as from the introduction of a foreign agent such as serum, vaccine, antigenic substance or organism. "Beyond the influence of pre‐existing anti‐E antibodies, our findings indicate that the anti‐NS1 produced during infection and the production of host cytokine IL‐6 are associated with the stimulation of antiviral immune response." (PMID 41488232, 2026). "Infection with the multi-deletion mutants also caused significant reductions in IL-6 secretion compared to WT, despite infection with als3∆/∆, hgc1∆/∆, and sap2∆/∆ single mutants not causing significant differences." (PMID 41294335, 2026). "The results imply that IL‐6 expression not only differentiates between early primary and secondary infections but also has potential associations with pre‐existing antiviral immunity." (PMID 41488232, 2026). "Several of these cytokines also correlated significantly with IL‐6, indicating an IL‐6–centered immune signature linked to infection status and pre‐existing immunity." (PMID 41488232, 2026). "Patients have elevated levels of IL-6, IL-12, IL-1β, and other proinflammatory cytokines that contribute to infection clearance but at high levels cause severe, even fatal disease." (PMID 41400356, 2026). "Perhaps most promisingly, emerging biomarkers-particularly interleukin-6, interleukin-10, and procalcitonin-have substantially enhanced our ability to stratify infection risk, demonstrating sensitivity exceeding 85% for bacteraemia detection." (PMID 42042690, 2026). "For anti-IL-6 bDMARDs, a history of infections requiring hospital treatment was associated with an earlier start with the treatment." (PMID 39698233, 2025). "As in hippocampi, mother’s infection with H1N1pdm09 was associated with Il6 upregulation in total brain tissues." (PMID 41567998, 2025). "Infiltrating immune cells following an infection are activated by inflammatory cytokines such as IL-1, IL-6, and TNF-α, which are implicated in RMSF pathology." (PMID 41159782, 2025). "The important role of this interleukin in controlling infections is indicated using anti-IL-6 immunotherapy, which increases the susceptibility of patients to infections." (PMID 40647668, 2025). "In immunocompromised patients, especially FL patients with B lymphocyte deficiency, hypogammaglobulinemia, and low expression of IL‐6 in peripheral blood, inconsistent with clinical infection symptoms." (PMID 40977416, 2025). "Myd88-deficiency attenuated secretion of IL-6 and TNFα upon infection with CFT073, while tlr4-deficiency almost completely abolished secretion of both cytokines." (PMID 41310197, 2025). "The rapid production of IL-6 contributes to host defense during infection and tissue injury, but excessive synthesis of IL-6 and dysregulation of IL-6 receptor signaling are associated with disease pathology." (PMID 40061954, 2025). "Gene expression of pro-inflammatory cytokines IL-1β, IL-2, IL-4, and IL-6, as well as IFNγ was significantly upregulated in nasal turbinates in response to infection with all VOCs, with the Gamma variant inducing the highest inflammatory response." (PMID 40295859, 2025). "Our vaccination protocols that resulted in significant protection against infection induced the expression of multiple cytokines including IL-6, IFN-γ, TNF and IL-17, which have been associated with a more effective control of T. cruzi infection." (PMID 41181325, 2025). "Elevated interleukin 6 (IL-6) and reduced platelet counts at the time of first infection were shown to be associated with a higher risk of in-hospital mortality." (PMID 40104588, 2025). "Infection with SARS-CoV-2 virus causes an amplification of inflammatory cytokines (IL-6 and IFN-γ being expressed in children), which are in fact immune cells that are directed to the site of infection affecting the lungs through tissue destruction." (PMID 40648899, 2025).